LGR5 (leucine rich repeat containing G protein-coupled receptor 5)
Diseases named in the same sentence as LGR5 in open-access papers (continued):
Sharing a sentence is not in itself a finding about the gene and the disease.
cancer (continued). "Our data demonstrate a molecular signature expression for ABCB5 and Lgr5 as gene profile for cancer cells with specific characteristics for chemo resistance and self-renewal in the bone marrow of patients with CRC." (PMID 34221246, 2017). "In line with the observed reduction of CD133 and CD44 expression, in HCT116 cells Rimonabant downregulates Lgr5, suggesting a potential role of the compound in the control of cancer stemness." (PMID 29354056, 2017). "The two organoids recapitulated their corresponding clinical samples in terms of 3D structure and immmunoistochemical profile and were positive for the cancer stem cells marker LGR5." (PMID 28114961, 2017). "If human cancer cells with rainbow construct would be available, in vitro lineage-tracing using these must be helpful to investigate the manner how Bmi1+ - or Lgr5+-cells clonally expand in human intestine tumors." (PMID 28176811, 2017). "Remarkably, a consistent finding is that LGR5 overexpression in cancer cells alters the actin cytoskeleton structure and increases cell–cell adhesion in the absence of endogenous or exogenous RSPO stimulation." (PMID 28739799, 2017). "Expression of Lgr5 protein was found predominantly in the cytoplasm and membrane of cancer cells, with some nucleus staining." (PMID 28404917, 2017). "The mean relative expression of Lgr5 protein was 0.672±0.199 for cancer and 0.135±0.039 for adjacent normal mucosa." (PMID 28404940, 2017). "Addressing this issue is critical, as Lgr5 is currently under investigation as a clinical target for treatment of cancers and other Wnt-related diseases." (PMID 28649656, 2017). "All these findings suggested that Lgr5 positive cells play a key role in invasion and metastasis in cancer." (PMID 28404940, 2017). "Recent advances in organoid technology and analytical modalities have enabled precise characterization of Lgr5+ intestinal stem cells, providing insights into their roles in homeostasis and cancer." (PMID 28720124, 2017). "In the current study, we addressed these questions as a follow-up study of our recent report, which demonstrates the importance of Lgr5-positive CRC cells in cancer growth." (PMID 27835894, 2016). "The GC cells transfected with LGR5 showed significantly enhanced cell proliferation, sphere cell growth, cancer cell migration, and drug resistance." (PMID 28033430, 2016). "Like cancer cells, LGR5+ SC are capable of anchorage-independent and clonogenic growth, yet the malignant potential conferred by LGR5 per se remains controversial." (PMID 26744320, 2016). "To further confirm that LGR5 can promote cancer cell migration and even metastasis, we performed a cell migration assay with LGR5-transfected MGC803 cells and the mock-transfected control cells." (PMID 28033430, 2016). "Hypoxia gradually reduced SCEL expression in cancer cells, while the levels of vimentin and Lgr5 were increased and the epithelial marker E-cadherin was reduced." (PMID 27013588, 2016). "LGR5, under the regulation of Wnt pathway, was proposed as a stem cell marker and its expression has been found to be overexpressed in various cancer tissues." (PMID 27816053, 2016). "Challenge of PANC-1 cells with GEM increased the expression of stemness markers including CD133, nestin and Lgr5 and promoted sphere forming activity suggesting chemotherapy enriched cancer cells with stem-like properties." (PMID 27531902, 2016). "The Lgr5+ cancer cells transduced with AAV-pLgr5-LUC-GFP expressed both luciferase (LUC) and GFP reporter." (PMID 27835894, 2016). "LGR5 is overexpressed in several types of cancer and can promote the growth/metastasis of colon tumor cells." (PMID 27049829, 2016). "To explore if LGR5 can enhance cancer cell expansion and survival and reduce apoptosis, we conducted a cell proliferation assay with LGR5-transfected MGC803 cells and mock-transfected control cells." (PMID 28033430, 2016).
cancer (continued). "The use of both CD133 and Lgr5 as surrogate markers for CSCs in BC and other cancer types has been demonstrated previously." (PMID 26683522, 2016). "As LGR5 promotes malignant transformation, its absence in LGR5− carcinomas suggests the presence of another oncogenic driver." (PMID 26744320, 2016). "Gene clusters upregulated at the NE towards E-RG stage were enriched for nervous system morphogenesis (P=1.2E−7) and cancer associated factors (P=6.9E−8) and included genes such as NR2E1 and LGR5." (PMID 25799239, 2015). "Functionally, enhanced lgr5 expression promoted cancer cell proliferation and tumorigenicity, while the silencing of lgr5 reduced proliferation, migration and colony formation, tumorigenicity and induced cellular apoptosis." (PMID 26599100, 2015). "For HTS, we chose Lgr5 as a prototype since we are interested in its unique trafficking properties, its role in stem cell biology and cancer, and its history as a difficult target to study." (PMID 26678094, 2015). "In the human intestine, OLFM4 was identified as a robust marker of LGR5+ stem cells and a subset of cancer cells." (PMID 26561938, 2015). "LGR5 is a marker of normal and cancer stem cells in various tissues where it functions as a receptor for R-spondins and increases canonical Wnt signalling amplitude." (PMID 26517508, 2015). "Leucine-rich repeat-containing G-protein-coupled receptor 5 (LGR5) is a cancer stem cell marker and a down-stream target in Wnt/β-catenin signaling." (PMID 26416247, 2015). "Lgr5 has been suggested to be involved in cancer progression through regulation of the Wnt signaling pathway." (PMID 24666414, 2014). "High LGR5 expression has been extensively reported to be an unfavorable prognostic indicator in various human cancers." (PMID 25192390, 2014). "ARID3B induced expression of genes associated with metastasis and cancer stem cells (CD44, LGR5, PROM1 (CD133), and Notch2)." (PMID 25327563, 2014). "Recently, elevated LGR5 expression has been observed in several types of cancers, including hepatocellular carcinoma, CRC, ovarian cancer, and basal cell carcinoma." (PMID 25192390, 2014). "LGR5 expression was also expressed over areas of epithelium in carcinoma tissue, but expression levels were reduced in the carcinomas compared to adenomatous polyp." (PMID 25423035, 2014). "It is clear that the number of LGR5 expressing cells are markedly increased and easily detected in the epithelium of adenomatous polyps and carcinoma." (PMID 25423035, 2014). "This is supported by the participation of Lgr5 in supporting Wnt-driven intestinal adenomas in mouse, and cancer stem cells isolated from primary human colon tumors." (PMID 23950932, 2013). "The potentiation of Wnt/β-catenin signaling is now believed to mediate the self-renewal and proliferation of LGR5+ stem cells, both normal and malignant, and provides a mechanistic link between LGR5, Wnt signaling, cancer stem cells, and cancer progression." (PMID 23596566, 2013). "Tumors arising in villin-TLR4 mice are characterized by intense nuclear β-catenin staining and a population of Lgr5-positive cells, a marker of cancer stem cells." (PMID 23691015, 2013). "It has been previously reported that LGR5 expression is enriched in cancer cells with stem cell-like properties." (PMID 23596566, 2013). "This is reminiscent to the reported cooperation between TGF-β and Wnt pathways in GIF-14 cells that synergistically induced Lgr5, a strong amplifier of the Wnt signal that supports normal and cancer stem cells." (PMID 23950932, 2013). "Since this discovery, Lgr5 mediated lineage tracing has reliably identified stem cells in several other tissues and interestingly Lgr5 expression has been correlated with cancer." (PMID 24386388, 2013). "Another potential cancer stem cell marker Lgr5 was also studied and found to be affected in similar manner to DCLK1." (PMID 23533514, 2013).
cancer (continued). "Positive expression of Lgr5 was found in 83.1% (54/65) of stage III cancer tissues and 100% (10/10) of stage IV cancer tissues." (PMID 23153436, 2012). "Expression of Lgr5 protein was found mostly in the cytoplasm of cancer cells, with some membrane staining." (PMID 23153436, 2012). "Our study also showed that Lgr5 expression was positively correlated with Ki-67, a recognized nuclear antigen-specific marker of cellular proliferation, suggesting that Lgr5-positive cancer cells have higher proliferative activity." (PMID 23153436, 2012). "The corresponding carcinomas of the oesophagus, stomach, liver, pancreas, colon and rectum showed significantly more LGR5+ cells as well as significantly higher levels of LGR5-mRNA compared with the corresponding non-neoplastic tissue." (PMID 22530031, 2012). "For further investigation of the adoptive role of LgR5 in BE and its relation to potentially cancer-initiating cells in early BE, we analyzed proliferation status of LgR5 expressing early Barrett cells." (PMID 21345220, 2011). "Here, we investigated the prognostic impact of the stem cell marker, cancer-associated gene and Wnt/Tcf4 target gene LGR5/GPR49 in STS for the first time." (PMID 21978106, 2011). "Many of the differentially expressed genes are implicated in tumorigenesis, and 5 of the upregulated genes are involved in the WNT pathway (e.g. Fst, Lgr5, Sfrp1, Sfrp2, and Wisp2), which is dysregulated in a variety of cancers." (PMID 20429939, 2010). "We have previously demonstrated that Helicobacter pylori (Hp) (cagA+vacA+) contributes to GC development by activating gastric fibroblasts toward CAF-like phenotype, eliciting aggressive, cancer stem cells (CSCs)-related malignant transformation of LGR5+ normal epithelial cells." (PMID 41597243, 2026). "Our initial pilot experiments with α-LGR5 bispecific bode well for treatment of LGR5+ cancers." (PMID 40405910, 2025). "Cancer therapy itself also appears to have an impact on the LGR5+ cell population." (PMID 40427162, 2025). "Importantly, CDH17 supports clonogenicity and cancer stemness by regulating LGR5, a Wnt-targeted gene and established intestinal stem cell marker." (PMID 41155133, 2025). "However, the lack of suitable, well-validated, available antibodies has hampered both the detection of LGR5 expression in cancers and the development of LGR5-targeted therapies so far." (PMID 40405910, 2025). "Moreover, our assessment of cancer stemness relied on staining of well-defined markers LGR5 and CD133." (PMID 41390849, 2025). "The plasticity of LGR5+ cancer stem cells (CSCs) is particularly notable; these cells can dynamically transition between proliferative, invasive, and quiescent states in response to microenvironmental cues, such as WNT ligands, inflammatory cytokines, and hypoxia." (PMID 41002393, 2025). "The plasticity and potential of LGR5 (+) cancer stem cells could provide therapeutic targets for cancer." (PMID 41194856, 2025). "The greater efficacy observed, as compared to historical studies of standard control therapies, may reflect a more effective targeting and elimination of the LGR5+ subset of cells within the cancer that may drive cancer growth and metastases." (PMID 40427162, 2025). "Multiple lines of evidence support a role for LGR5 in cancer." (PMID 40427162, 2025). "Knocking out p57+Lgr5+ cancer stem cells substantially reduces CRC recurrence after treatment." (PMID 41346579, 2025). "Recent advances in the field have focused on novel biomarkers for cancer stem cell identification, such as Lgr5 (a G-protein-coupled receptor), that could eventually be targeted in an attempt to reverse this innate resistance of tumors to chemotherapy and RT." (PMID 40002930, 2025). "Furthermore, the high CBLL1 expression observed in the tumourspheres was accompanied by the upregulation of other established cancer stem cell markers, including LGR5, NANOG, SOX2, KLF4 and c-MYC mRNA levels." (PMID 38339195, 2024).
cancer (continued). "Importantly, we demonstrate robust pre-clinical efficacy of α-LGR5 in all three therapeutic modalities in a murine model of human pre-B-ALL thus supporting continued development of α-LGR5-based immune therapies for all LGR5-expressing cancer types." (PMID 39169164, 2024). "Similarly, studies support a link between Fusobacterium nucleatum and colorectal tumors attributed to the increased presence of Lgr5+ cancer cells." (PMID 38903529, 2024). "“It is unclear how this differential expression of LGR5 isoforms may promote the development of human cancers, particularly with regard to the regulation of Wnt/β-catenin activity”." (PMID 39769183, 2024). "In addition, the development of new therapeutic strategies or modification of existing strategies to cover Lgr5+ CSCs and overcome cancer cell plasticity is required for the effective treatment of CRC at different stages." (PMID 39183418, 2024). "Firstly, LGR5 targeting could potentially eliminate cancer stem cells that are responsible for relapse and metastasis." (PMID 39417449, 2024). "Additionally, the Wnt pathway’s link to cancer stem cells (CSCs), marked by Lgr5, emphasizes Lgr5’s role as a biomarker in cancer progression and drug resistance." (PMID 39684755, 2024). "Additionally, LGR5 has been identified as a significant marker for cancer stem cells (CSCs), highlighting its relevance in cancer research and its prospective applications in therapeutic strategies." (PMID 39684513, 2024). "Moreover, CBLL1 silencing on cancer stem cell tumourspheres induces a significant reduction in tumoursphere size, which is accompanied by the downregulation of the stem cell biomarkers LGR5 and c-MYC at both mRNA and protein levels." (PMID 38339195, 2024). "TCF7L1 may play a specific role in repressing LGR5 expression in a subpopulation of cells to regulate cancer stem cell plasticity." (PMID 36833408, 2023). "Lgr5 is a target of Wnt signaling, and a selective and ideal cancer stem cell marker." (PMID 36797277, 2023). "Mechanism studies elucidated that METTL3 could increase CBX8 mRNA stability dependent on IGF2BP1, and then CBX8 promotes the transcription of leucine rich repeat containing G protein-coupled receptor 5 (LGR5) to maintain cancer stemness and chemoresistance." (PMID 36810281, 2023). "ALDH1, CD133, CD44, Lgr5, Msi-1, and EphB1 are markers of cancer stemness." (PMID 36797277, 2023). "Another study in CRC reported that LGR5+ and LGR5− cancer cells can give rise to liver metastasis." (PMID 37578396, 2023). "To examine whether the crude extract and 1′-O-methyl-averantin inhibit expression of cancer stemness markers in CSC221 cells, we measured expression of mRNA encoding ALDH1, CD133, CD44, Lgr5, Msi-1, and EphB1." (PMID 36797277, 2023). "Therefore, it seems that LGR5 expression can be regulated by signaling pathways other than Wnt/β-catenin depending on the type of cancer." (PMID 35778589, 2022). "Furthermore, Lgr5+ cancer cells have been shown to serve as so-called cancer stem cells in growing cancer tissues." (PMID 35778589, 2022). "Although LGR5 has been regarded as a promising cancer stem cell marker, its biological behavior may be different from other cancer stem cell markers; the exact function of LGR5 remains unclear." (PMID 35123536, 2022). "LGR5 marks resident adult epithelial stem cells at the gland base in the mouse pyloric stomach (157 144), and LGR5+ intestinal stem cells are major sources of cancer cell generation following hyperactivation of the WNT pathway, a key regulator of stem cell behavior." (PMID 35847914, 2022). "LGR5 is a promising marker of intestinal stem cells and cancer stem cells." (PMID 33462260, 2021).
cancer (continued). "An abnormal increase in LGR5 expression may represent one of the most common molecular changes in some human cancers, resulting in long-term enhancement of canonical Wnt/β-catenin signaling." (PMID 33462260, 2021). "Alternatively, the induced LGR5 expression in the myoepithelium might be the consequence of intricate interactions between the myoepithelium and cancer cells." (PMID 34493772, 2021). "LGR5 overexpression promotes treatment resistance and cancer stemness in both brain tumors and CC." (PMID 34452555, 2021). "Lgr5+ CRC cells and Lgr5- cancer cells are known to be interconvertible." (PMID 35582377, 2021). "Our results suggest that high expression levels of LGR5 are correlated with more malignant tumors." (PMID 34582650, 2021). "Furthermore, the appearance of Lgr5+ CSCs is indispensable for the outgrowth of metastases founded by Lgr5− cancer cells." (PMID 34572727, 2021). "Lgr5 + stem cell mRNA is more expressed in the crypt bottom during cancer growth." (PMID 33827616, 2021). "Additionally, in studies using RNAscope, high LGR5 expression is correlated with well-differentiated cancer." (PMID 33676447, 2021). "HNK also suppressed the expression of additional cancer stem cell marker proteins LGR5 and CD44." (PMID 34206989, 2021). "KEGG pathway analyses revealed differential expression in curcumin-treated LGR5(+) cells involved in ‘Pathways in cancer,’ ‘PI3K-Akt signaling pathway,’ ‘MAPK signaling pathway,’ ‘Wnt signaling pathway,’ ‘NF-kappa B signaling pathway,’ ‘ECM-receptor interaction,’ and ‘Lysosome’ (Data not shown)." (PMID 33713277, 2021). "Results from a TCGA (The Cancer Genome Atlas) database analysis and immunohistologic staining revealed that intestinal adenocarcinomas of the gastric antrum and gastroesophageal junction were accompanied by the expansion of Lgr5." (PMID 33043003, 2020). "However, by using the novel PDT method and by taking advantage of the localization of cancer stem cells, we selectively eliminated Lgr5+ cells near the colon luminal surface, which are highly likely to be CSCs." (PMID 31947553, 2020). "Interestingly, in this minimal medium we were able to grow organoids from Lgr5− circulating cancer cells, and also here we observed the appearance of Lgr5+ CSCs over time." (PMID 32169167, 2020). "Furthermore, we found this phenotype to be associated with both increased numbers of crypt-based Lgr5+ CBC cells and exacerbated stemness, inflammatory and cancer-related gene expression programs in this cellular context." (PMID 32948837, 2020). "Inferring from studies on hair follicle stem cells, nuclear Lgr5 may be highlighting the cancer cells with a yet a different pattern of “stemness”." (PMID 32894084, 2020). "However, the expression of Lgr5 in normal stem cells makes it difficult to prove the efficacy of therapies targeted exclusively at Lgr5+ cancer cells." (PMID 31947553, 2020). "Escaping Lgr5- cancer cells are highlighted with dashed lines." (PMID 32169167, 2020). "Reexpression of Lgr5 allows cancer cells to decrease the clonogenicity and tumorigenicity." (PMID 31901081, 2020). "Similarly, nuclear Lgr5 positivity was seen more frequently with better differentiated cancers (8/34 in grade 1–2 vs. 10/61 in grade 3–4), but the difference was not statistically significant." (PMID 32894084, 2020). "First, our study revealed the high expression of Lgr5 to be correlated with vascular invasion, which may indirectly indicate the presence of some unknown mechanism that may contribute to the ability of cancer cells to invade the vessels." (PMID 32671503, 2020). "Using the developed orthotopic transplantation mouse model, we addressed whether Lgr5+ CSCs and Lgr5− cancer cells have differential metastatic behavior." (PMID 32169167, 2020). "Escaping Lgr5+ cancer stem cells are highlighted with dashed lines." (PMID 32169167, 2020).